PRKAG1 (protein kinase AMP-activated non-catalytic subunit gamma 1)
Description:
AMP/ATP-binding subunit of AMP-activated protein kinase (AMPK), an energy sensor protein kinase that plays a key role in regulating cellular energy metabolism. In response to reduction of intracellular ATP levels, AMPK activates energy-producing pathways and inhibits energy-consuming processes: inhibits protein, carbohydrate and lipid biosynthesis, as well as cell growth and proliferation. AMPK acts via direct phosphorylation of metabolic enzymes, and by longer-term effects via phosphorylation of transcription regulators. Also acts as a regulator of cellular polarity by remodeling the actin cytoskeleton; probably by indirectly activating myosin. Gamma non-catalytic subunit mediates binding to AMP, ADP and ATP, leading to activate or inhibit AMPK: AMP-binding results in allosteric activation of alpha catalytic subunit (PRKAA1 or PRKAA2) both by inducing phosphorylation and preventing dephosphorylation of catalytic subunits. ADP also stimulates phosphorylation, without stimulating already phosphorylated catalytic subunit. ATP promotes dephosphorylation of catalytic subunit, rendering the AMPK enzyme inactive.
Synonyms: AMPKg
Tractability: Small molecule: a drug acting on it is in phase 2 or 3 trials; a structure with a bound ligand is known; a high-quality ligand is known; it has a binding pocket of medium quality. PROTAC: ubiquitination databases record sites on it; its protein half-life has been measured; a small molecule that binds it is known.
Target class: Kinase; Protein kinase regulatory subunit; Enzyme
Safety:
Unwanted effects reported when the protein is acted on. In parentheses: how it was acted on, where the effect was seen, and who reports it.
heart disease (cardiovascular system; source: Force et al. (2011))
Gene: Protein-coding gene on chromosome 12 (49,002,274 to 49,018,807, reverse strand). Ensembl gene ENSG00000181929.
Subcellular location (Human Protein Atlas): Cytosol; Nuclear bodies; Basal body; Nucleoplasm
Pathways (Reactome):
Autophagy: Lipophagy; Macroautophagy
Immune System: AMPK-induced ERAD and lysosome mediated degradation of PD-L1(CD274)
Neuronal System: Activation of AMPK downstream of NMDARs
Organelle biogenesis and maintenance: Activation of PPARGC1A (PGC-1alpha) by phosphorylation
Signal Transduction: Energy dependent regulation of mTOR by LKB1-AMPK
Vesicle-mediated transport: Translocation of SLC2A4 (GLUT4) to the plasma membrane
Gene Ontology:
Molecular function: protein binding; protein kinase binding; protein kinase regulator activity; ADP binding; AMP binding; ATP binding; cAMP-dependent protein kinase activity; cAMP-dependent protein kinase regulator activity; AMP-activated protein kinase activity; protein-containing complex binding
Biological process: cellular response to nutrient levels; positive regulation of gluconeogenesis; protein phosphorylation; regulation of cell cycle; regulation of glycolytic process; signal transduction; spermatogenesis
Cellular component: membrane; nucleotide-activated protein kinase complex; nucleus; cytoplasm; cytosol; endoplasmic reticulum lumen; nucleoplasm; protein-containing complex
Genetic constraint (gnomAD): Loss-of-function variants: 27 observed, 50.64 expected, observed/expected ratio (o/e) 0.53, 90% interval 0.39 to 0.74. The upper end of that interval is the gene's LOEUF score, 0.74, which puts it in group 3 of 6, group 1 being the genes least tolerant of losing a copy. Missense variants: 287 observed, 419.9 expected, observed/expected ratio (o/e) 0.68, 90% interval 0.62 to 0.75. Synonymous variants: 130 observed, 156.26 expected, observed/expected ratio (o/e) 0.83, 90% interval 0.72 to 0.96.
Homologues: Orthologues: macaque PRKAG1 (99% identical), dog PRKAG1 (98% identical), guinea pig PRKAG1 (97% identical), mouse Prkag1 (97% identical), rat Prkag1 (96% identical), chimpanzee PRKAG1 (95% identical), pig PRKAG1 (90% identical), tropical clawed frog kmt2d (80% identical), zebrafish prkag1 (80% identical), Caenorhabditis elegans aakg-2 (36% identical), Caenorhabditis elegans aakg-3 (32% identical). Paralogues in human: PRKAG2 (72% identical), PRKAG3 (59% identical).
Diseases named in the same sentence as PRKAG1 in open-access papers:
PRKAG1 is named in the same sentence as 21 diseases in open-access papers, as found by Europe PMC text mining. Sharing a sentence is not in itself a finding about the gene and the disease. The quoted sentences say what the papers report.
colorectal cancer (2 papers, 2016 to 2026). A primary or metastatic malignant neoplasm that affects the colon or rectum. "PRKAG1 was associated with a reduced risk of colorectal cancer (OR: 0.74 per mmol/mol reduction in overall HbA1c, 95% CI: 0.63-0.87; p = 0.001), with consistent findings in sex-specific analysis." (PMID 41755790, 2026).
Obesity (2 papers, 2018 to 2023). Accumulation of substantial excess body fat. "We observed a nominally significant association for only two T2D markers in RREB1 and PRKAG1, one obesity (OB) marker in the OR2Y1 gene, and for several BMI markers in the ACP1, RBBP6, and C14orf39 genes." (PMID 30126146, 2018).
breast carcinoma (1 paper, 2021). "Further analysis also revealed that Pdcd1 was negatively correlated with AMPK subunit mRNAs including Prkaa1, Prkaa2, and Prkag1 in TCGA database obtained from prostate, melanoma, and breast cancer patients." (PMID 34649584, 2021).
heart failure (1 paper, 2024). Inability of the heart to pump blood at an adequate rate to meet tissue metabolic requirements. "Contrastingly, in this cohort, expression of proteins associated with AMPK-encoding genes (PRKAA1, PRKAG1, PRKAA2, PRKAB1, PRKAB2 and PRKAG2) are significantly higher in oHCM patients, compared with other heart failure aetiologies, and expression of ALDOA is significantly down-regulated." (PMID 39200175, 2024).
liver cancer (1 paper, 2025). An epithelial or non-epithelial malignant neoplasm that arises from the liver. "By integrating transcriptome data from TCGA liver cancer samples, we systematically evaluated the correlation between PRKAG1 expression and immune cell infiltration in the tumor microenvironment using multiple algorithms (EPIC, TIMER, TIDE, and MCPCOUNTER)." (PMID 40958861, 2025).
cancer (4 papers, 2016 to 2026). A tumor composed of atypical neoplastic, often pleomorphic cells that invade other tissues. "Dysregulation of AMPK pathway components has been linked to the progression of various cancers, yet the precise mechanistic role of PRKAG1 in tumor biology warrants further investigation." (PMID 40958861, 2025). "Results showed that PRKAG1 expression was positively correlated with the infiltration of CD4+ T cells, CD8+ T cells, B cells, and cancer-associated fibroblasts." (PMID 40958861, 2025).
tumor (1 paper, 2025). "CIBERSORT analysis showed that PRKAG1 expression significantly affected the composition and abundance of immune cells in the tumor microenvironment." (PMID 40958861, 2025). "Meanwhile, immunohistochemical results showed high PRKAG1 expression in tumor tissues, providing an important basis for subsequent exploration of PRKAG1’s mechanism of action." (PMID 40958861, 2025). "Given the close association between the tumor immune microenvironment and carcinogenesis, analysis of the HPA database showed significant differences in PRKAG1 expression across different tissues and cell types." (PMID 40958861, 2025). "Systematic analysis using the CellPhoneDB algorithm showed that PRKAG1-expressing cells were more likely to establish communication networks in the tumor microenvironment." (PMID 40958861, 2025). "Using single-cell RNA sequencing technology, we systematically analyzed the differential expression patterns of PRKAG1 in various cells from tumor tissues and adjacent normal tissues." (PMID 40958861, 2025). "Results showed that in the tumor microenvironment, PRKAG1 was significantly highly expressed in hepatocytes and monocytes (P<0.05); in adjacent normal tissues, PRKAG1 was mainly enriched in T cells and myeloid cells (P<0.05)." (PMID 40958861, 2025). "This “metabolic-immune” cross-regulation provides experimental evidence for the “metabolic checkpoint” theory and highlights the dual expression characteristics of PRKAG1 in immune cells and tumor cells." (PMID 40958861, 2025). "Results showed that the tumor size and volume in the Hepa1-6-shPRKAG1 group were significantly smaller than those in the Hepa1-6-shNC group, intuitively indicating that PRKAG1 knockdown could effectively inhibit the growth of HCC xenografts." (PMID 40958861, 2025). "ESTIMATE algorithm analysis showed that the stromal score of the high PRKAG1 expression group was significantly reduced (P<0.05), indicating that PRKAG1 may participate in the remodeling of the tumor microenvironment by regulating immune-stromal interactions." (PMID 40958861, 2025). "Additionally, the precise mechanism by which PRKAG1 influences the tumor immune microenvironment needs further investigation." (PMID 40958861, 2025). "Notably, the expression pattern of PRKAG1 in tumor tissues was similar to its distribution in normal tissues, also showing low tumor specificity." (PMID 40958861, 2025). "PRKAG1, as a downstream target of MALAT1, was also highly expressed in HCC and correlated with tumor stage and adverse outcomes." (PMID 40958861, 2025). "This study is the first to confirm that MALAT1 upregulates PRKAG1 expression by sponging miR-383-5p to promote HCC, consistent with the tumor-suppressive role of miR-383-5p." (PMID 40958861, 2025). "This study elucidates the oncogenic role of the MALAT1/miR-383-5p/PRKAG1 axis in HCC, demonstrating that PRKAG1 promotes tumor progression by regulating cell proliferation, the immune microenvironment, and key signaling pathways." (PMID 40958861, 2025). "Additionally, PRKAG1, a regulatory subunit of AMPK, has an unclear function in tumor progression." (PMID 40958861, 2025).
PRKAG1 also shares sentences with these, for which no sentence is quoted: age (1 paper); cholangiocarcinoma (1); colon adenocarcinoma (1); epilepsy (1); glioblastoma multiforme (1); head and neck squamous cell carcinoma (1); hepatocellular carcinoma (1); hereditary cardiomyopathies (1); lung adenocarcinoma (1); lung squamous cell carcinoma (1); melanoma (1); prostate carcinoma (1); Splenomegaly (1); type 2 diabetes (1).